LINC01519 (long independently transcribed non-coding RNA 1519)
Gene: Long non-coding RNA gene on chromosome 10 (85,193,418 to 85,199,259, reverse strand). Ensembl gene ENSG00000237267.
Diseases named in the same sentence as LINC01519 in open-access papers:
LINC01519 is named in the same sentence as 1 disease in open-access papers, as found by Europe PMC text mining. Sharing a sentence is not in itself a finding about the gene and the disease. The quoted sentences say what the papers report.
thyroid cancer (1 paper, 2018). "The results of CNV analyses showed that many differentially expressed lncRNAs loci are accompanied with copy number amplification or deletion, such as LINC01354 and LINC01341 have frequency gain, LINC00595 and LINC01519 have frequency loss in thyroid cancer." (PMID 29923329, 2018). "Moreover, some of those dysregulated lncRNAs genomic loci contains copy number amplification or deletion, such as LINC01354, LINC01341, LINC00595, and LINC01519, suggesting that genomic alterations might involve in part of these lncRNAs dysregulation in thyroid cancer." (PMID 29923329, 2018).